NGF (nerve growth factor)
Diseases named in the same sentence as NGF in open-access papers (continued):
Sharing a sentence is not in itself a finding about the gene and the disease.
retinal degeneration (20 papers, 2009 to 2024). Degeneration of the retina. "In the present paper, the potential of a variant of NGF has been tested for the first time as a treatment for retinal degeneration in a well-established mouse model of RP." (PMID 39293937, 2024). "In 1996, Lambiase and Aloe showed that intravitreal and retrobulbar injection of NGF caused a significant delay of retinal degeneration with preservation of the outer nuclear layer (ONL) in C3H mice." (PMID 26748988, 2016). "As already showed by means of different models of retinal degenerations, ed-NGF are able to counteract RGC loss, and exerts protective and reparative actions through the normalization of neurotrophins and expression of TrkA receptors and its related intracellular pathways." (PMID 36291113, 2022). "PNA, a lectin from Arachis hypogea, is widely known to selectively recognise and bind cone photoreceptors, while NGF is a neurotrophin with established activity in counteracting retinal degeneration." (PMID 37111581, 2023). "Taking advantage of the evidence collected, we decided to perform a double conjugation onto the polyacrylamide nanoparticles’ surface using the NGF as a neuroprotective molecule against retinal degeneration." (PMID 37111581, 2023). "The neuroprotective activity of ANP:PNA:NGF was assessed in an oxidative stress-induced retinal degeneration model using the teleost zebrafish." (PMID 37111581, 2023). "We suggested that retinal degeneration in OXYS rats progresses even in the presence of compensatory upregulation of NGF." (PMID 30871541, 2019). "We propose that proNGF and p75NTR contribute to exacerbate retinal degeneration by further stimulating apoptosis during the second week after injury, and thus hamper the neuroprotective effect of the endogenous NGF." (PMID 28067793, 2017). "Administration of exogenous NGF has been shown to ameliorate retinal degeneration." (PMID 35223834, 2022). "We evaluated the NGF effect on optic nerve and retina degeneration by estimating the number of ganglion cells 75 days after 2VO legation, and by measuring the optic nerve diameter, and the beta-tubulin- and MBP-immunostained area fraction over the optic nerve transverse section." (PMID 19473529, 2009). "As the retinal degeneration starts, the activated microglia invade the degenerated photoreceptor layer and reduce the expressions of neurotrophic factors including nerve growth factor (NGF), ciliary neurotrophic factor (CNTF), and glial cell line-derived neurotrophic factor (GDNF)." (PMID 37728589, 2024). "Ed-NGF treatment in diabetic rats reversed the downregulation of intracellular signals, and inhibited the accumulation of proNGF, thus confirming that the increase in NGF availability counteracts the events which might favor the progression of retinal degeneration, as suggested by previous works." (PMID 36291113, 2022). "The highest SF3/SF1 proteins are known to have antioxidant effects, including NGF, BDNF, PEDF, and LIF, suggesting that SF3 would have greater antioxidant effects and efficacy in models of retinal degeneration." (PMID 37443724, 2023). "NGF has been found to modulate retinal gliosis and decrease GFAP levels in different models of retinal degeneration or injury." (PMID 30006508, 2018). "In order to determine whether IV injection of rhNGF led to the activation of NGF canonical pathway, we analyzed the changes in ERK protein expression levels, a known NGF downstream effector, after light-induced retinal degeneration." (PMID 35330834, 2022). "Reduction or lack of available mature NGF results in RGC loss, which is manifested by a decrease in TrkA expression/activation, and Akt and/or ERK signaling disruption, as observed in different models of retina degeneration." (PMID 36291113, 2022).
retinal degeneration (continued). "However, it is important to take into consideration that in our study the treatment with ed-NGF started in the early stages of retinal degeneration following STZ administration, when the gliosis is still not present, and there is a low grade of vascular impairment." (PMID 36291113, 2022).
autoimmune disease (19 papers, 2010 to 2024). A disorder resulting from loss of function or tissue destruction of an organ or multiple organs, arising from humoral or cellular immune responses of the individual to their own tissue constituents. "Genetic mutations affecting the production of the NGF or mutations in the tropomyosin receptor kinase (TrkA) receptors might be implicated in autoimmune diseases." (PMID 38791953, 2024). "Genetic mutations affecting the production of NGF, or mutations in the receptors Trk and p75NTR, may potentially play a role in autoimmune diseases, particularly through their impact on the immune system and inflammation." (PMID 37998739, 2023). "More recently, NGF has been associated to inflammation and autoimmune diseases." (PMID 29334986, 2018). "Nevertheless, the precise role of NGF in autoimmune diseases remains incompletely understood, necessitating further research to establish the exact relationship between NGF and these conditions." (PMID 37998739, 2023). "The NGF and NTs levels are often used as markers of successful treatment in neurodegenerative and autoimmune diseases." (PMID 37998739, 2023). "The primary objective of this study is to provide a comprehensive summary of the existing literature regarding the involvement of NGF in autoimmune diseases." (PMID 37998739, 2023). "The involvement of NGF and p75NTR in the immune response was initially observed in inflammatory and autoimmune diseases, inducing the activation of immune cells and promoting increased cytokine production." (PMID 35746645, 2022). "In inflammatory and autoimmune diseases, a localized increase in NGF is observed at sites of inflammation." (PMID 36298702, 2022). "Further studies are needed to investigate the effects of NGF autoantibodies on the expression of NGF and its receptors in autoimmune disease." (PMID 29867937, 2018). "Several in vivo and in vitro studies establish the extra-neuronal role of nerve growth factor (NGF) in autoimmune diseases and illustrate the contribution of NGF in the acquired immune response." (PMID 25876154, 2015). "Enhanced production of NGF has been reported in inflamed tissues of patients with inflammatory and autoimmune diseases, but the reasons why NGF concentration is enhanced and how this can affect inflammatory responses are far from being fully understood." (PMID 23190582, 2012). "In this narrative review, we discuss scientific evidence on the role of NGF in autoimmune diseases." (PMID 37998739, 2023). "It is important to recognize that NGF is just one of numerous factors that may contribute to the development and progression of autoimmune diseases, as these conditions are intricate and multifactorial." (PMID 37998739, 2023). "Inversely, there are several other studies which, in the serum, synovial fluid, cerebrospinal fluid and tissue samples of patients of various autoimmune diseases find levels of NGF that are either elevated compared to healthy individuals, or even correlated to disease activity." (PMID 34305928, 2021). "Different inflammatory and autoimmune diseases lead to altered expression of NGF." (PMID 29867937, 2018). "NGF is also known to be involved in some autoimmune disorders." (PMID 28447608, 2017). "Considering that no reported experimental data support the involvement of NT4/5 in B and T cell activation or autoimmune disease, this study mainly focused on the relationship between serum levels, B-lymphocyte expression of NGF, BDNF and NT-3, and SLE activity." (PMID 24223945, 2013). "Indeed, evidence indicates that NGF may play a role in the pathogenesis of autoimmune diseases." (PMID 37998739, 2023). "Although pro-inflammatory cytokines play a role in promoting NT secretion, other mechanisms are probably involved in NGF and BDNF release in autoimmune diseases." (PMID 21085492, 2010).
autoimmune disease (continued). "Indeed, growing evidence suggests that NGF, BDNF, and NT-3 participate in inflammatory responses, including the modulating and regulating immune function in inflammatory and autoimmune diseases." (PMID 24223945, 2013). "However, data concerning the influence of corticosteroid and/or immunosuppressive drugs on systemic levels of NGF and BDNF in autoimmune diseases are contradictory." (PMID 21085492, 2010). "Accumulating evidences suggest that NTs, especially Nerve Growth Factor (NGF) and Brain-Derived Neurotrophic Factor (BDNF), participate in inflammatory responses, including the modulation and regulation of immune functions in inflammatory and autoimmune diseases." (PMID 21085492, 2010).
bone cancer (19 papers, 2010 to 2025). A primary or metastatic malignant neoplasm affecting the bone or articular cartilage. "Treatment with anti-NGF antibodies significantly reduces the pain behavior associated with bone cancer." (PMID 36012155, 2022). "Given the impact of NGF in cancer pain, NGF blockade inhibits the sprouting of sensory nerve fibers and alleviates cancer-associated pain, especially bone cancer pain, through anti-hyperalgesia (i.e., normalizing a downregulated nociceptive threshold)." (PMID 33392191, 2020). "The association of nerve growth factor with bone neoplasms is related to its high-affinity receptor TrkA, and the gene encoding TrkA, NTRK1, may undergo fusion mutations, resulting in sustained activation of downstream pathways." (PMID 40860871, 2025). "Current clinical data show that NGF in bone neoplasms treatment mainly focuses on the treatment of neurogenic tumours and peripheral nerve injury, but its mechanism of action and potential application in bone tumours should not be ignored." (PMID 40860871, 2025). "One potential candidate to explain nerve sprouting in OA models is the neurotrophin, nerve growth factor (NGF), which has been shown to promote nerve sprouting in bone cancer and inflammatory models." (PMID 39076825, 2024). "Using a prostate-specific bone cancer model in a mouse femur, NGF-sequestering antibodies were administered." (PMID 36012155, 2022). "Nociceptive mediators/mechanisms common to oral cancer and bone cancer include, but are not limited to, endothelin, NGF, and PAR2." (PMID 34572924, 2021). "Treatment with an anti-NGF antibody significantly reduces bone cancer pain behaviors in a mouse model of femoral osteosarcoma." (PMID 33324652, 2020). "Sequestering NGF by systemic administration of anti-NGF antibodies can alleviate, in part, pain-like behaviors in animal models of bone cancer and fracture-induced pain and also inflammatory pain of other tissue systems." (PMID 28955292, 2017). "It has been suggested that BDNF is a key molecule in bone cancer pain, and the NGF-BDNF cascade reaction may be related to the occurrence of bone cancer pain." (PMID 39679363, 2024). "Both tumor and stromal cells contribute to the sensation of pain by secreting different factors that sensitize or stimulate primary afferent neurons, including NGF (nerve growth factor), which is fundamental in the genesis of bone cancer pain because of its effects on sensory neurons." (PMID 38791037, 2024). "In bone cancer, tumors and stromal cells within the bone marrow release chemical signals such as Nerve Growth Factor (NGF), Endothelin (ET), and hydrogen ions, which activate nociceptors, triggering electrical signals transmitted to the brain via the DRG and spinal cord." (PMID 39448865, 2024). "It was observed that the administration of a blocking antibody to NGF significantly reduced both early- and late-stage bone cancer pain-related behaviors to a level equivalent or greater to that observed following an acute administration of 10 mg/kg or 30 mg/kg of morphine sulfate." (PMID 36012155, 2022). "Additionally, administration of anti-NGF (mAb911) has also been shown to suppress functional connectivity alterations in a rodent model of bone cancer pain." (PMID 36258057, 2022). "However, the analgesic action of RBM-007 in bone cancer pain cannot be explained simply by reduced NGF activity, since RBM-007 is ineffective in a rat model of postoperative pain, in which anti-NGF aptamer is effective to attenuate postoperative pain." (PMID 34203430, 2021). "The blockade of NGF activity by a neutralizing antibody to NGF may lead to a considerable alleviation of both ongoing as well as movement-evoked bone cancer pain-related behaviors." (PMID 34203430, 2021). "This may explain why sequestering NGF after inflammatory pain has already developed attenuates pain behaviors in animal models of bone cancer and skeletal fracture." (PMID 28955292, 2017).
bone cancer (continued). "Hence, the pathophysiological role of FGF2 in bone cancer pain is largely independent from that of NGF." (PMID 27506449, 2016). "In addition, NGF has a promotional role in peripheral nerve regeneration, and the microenvironment of bone neoplasms is often accompanied by neural infiltration, which may affect tumour growth and metastasis." (PMID 40860871, 2025). "In bone cancer pain, short-term exposure of cancer-related fibroblasts, MSCs, and osteoblasts to pH 6.8 can promote the expression of inflammatory and nociceptive mediators (NGF, BDNF, IL-6, IL-8, IL-1b, and CCL5), leading to nociceptor sensitization and hyperalgesia." (PMID 39679363, 2024). "We assume that not only NGF but also FGF2 might be overexpressed by bone cancer." (PMID 27506449, 2016).
Down syndrome (19 papers, 2009 to 2025). "Recent studies pointed out that the NGF metabolic dysfunction is associated with AD and Down syndrome." (PMID 27350344, 2016). "Another interesting study found that increased doses of APP markedly decrease retrograde transport of nerve growth factor (NGF) and causes degeneration of forebrain cholinergic neurons in a mouse model of Down's Syndrome (DS)." (PMID 24224055, 2013). "Here, we present a brief overview of the characteristics of Alzheimer’s pathology in Down syndrome (DS) with an emphasis on this NGF metabolic pathway’s disruption during the evolving Alzheimer’s pathology." (PMID 34434101, 2021). "We also discuss the evidence of an early, preclinical, NGF metabolic dysregulation in the continuum of the AD pathology in sporadic cases as well as in Down syndrome (DS) with preclinical AD pathology." (PMID 35011577, 2021). "The discovery of an imbalance in the metabolic pathway controlling NGF maturation and degradation in Down syndrome/AD patients provides a platform for the identification of novel biomarker candidates as well for the development of disease-modifying drugs." (PMID 32296418, 2020). "Reduced retrograde transport of NGF has been demonstrated in animal models of aging and Down’s syndrome." (PMID 30853882, 2019). "In Down syndrome, the availability of mature NGF is compromised by diminished tPA/plasminogen → plasmin activity, which limits the production of NGF, further lowered by the increased activity of MMP-9 that degrades NGF." (PMID 29342922, 2018). "Diminished activity of tPA in Down syndrome brain converts less plasminogen to plasmin; this produces less proNGF to activate NGF." (PMID 29342922, 2018). "We show here that the overexpression of the Down syndrome-related genes Dyrk1A and Rcan1 reduce the effect of NGF on NFAT promoter activity and the upregulation of PAI-1 in PC12 cells." (PMID 23825664, 2013). "In a mouse model of Down’s syndrome (Trisomy 16), retrograde transport of radiolabelled NGF from the hippocampus to the septum was markedly reduced." (PMID 22654716, 2011). "Intriguingly, in a trisomic mouse model of Down's syndrome deletion of one copy of APP led to a marked improvement in transport of signaling endosomes containing NGF, reduced neurodegeneration, and improved cognitive function." (PMID 19348680, 2009). "It was reported that the nerve growth factor (NGF) metabolic pathway in Down syndrome is altered." (PMID 29342922, 2018). "We show that excess regulator of calcineurin 1 (RCAN1), an endogenous inhibitor of the calcineurin phosphatase that is triplicated in Down syndrome, impairs neurotrophic support of sympathetic neurons by inhibiting endocytosis of the nerve growth factor (NGF) receptor, TrkA." (PMID 26658127, 2015). "For instance, failed retrograde transport of nerve growth factor (NGF) from the hippocampus to the basal forebrain caused reduction in size and number of basal forebrain cholinergic neurons (BFCN) in the partial trisomy 16 (Ts65Dn) mouse model of Down’s syndrome." (PMID 28163671, 2017). "Notably, a strong correlation is present in Down syndrome cases showing preclinical AD among the plasma TNF-α increase, a deficit in NGF maturation (with grown concentrations of proNGF), and an increased degree of cognitive impairment." (PMID 32296418, 2020). "The present study shows that NGF regulates gene expression in neuronal cells through the calcineurin/NFAT pathway and that this effect is modulated by proteins that are overexpressed in Down syndrome." (PMID 23825664, 2013). "The authors concluded that the negative effect of DYRK1A and RCAN1 overexpression on NGF signal transduction in neural cells may contribute to the altered neurodevelopment and brain function in Down syndrome." (PMID 29342922, 2018). "The negative effect of DYRK1A and RCAN1 overexpression on NGF signal transduction in neural cells may contribute to the altered neurodevelopment and brain function in Down syndrome." (PMID 23825664, 2013).
Down syndrome (continued). "Nevertheless, given that the blood PAI-1 levels in Down syndrome individuals are lower than in controls we hypothesize that the attenuation of the NGF-induced PAI-1 by overexpression of DYRK1A and RCAN1 due to trisomy 21 may be relevant to several Down syndrome features." (PMID 23825664, 2013).
retinitis pigmentosa (19 papers, 2009 to 2025). Retinitis pigmentosa (RP) is an inherited retinal dystrophy leading to progressive loss of the photoreceptors and retinal pigment epithelium and resulting in blindness usually after several decades. "Topical administration of a highly purified recombinant human NGF facilitates the survival and regeneration of RGCs, and topical application of NGF has been already used for patients with retinitis pigmentosa in a clinical pilot study." (PMID 34445756, 2021). "Intravitreal injection of NGF has been used in the Royal College of Surgeons (RCS) rat model of retinitis pigmentosa, and the investigators believed the protective effect was associated with an increase in Trk-A and activated pTrk-A levels." (PMID 31208396, 2019). "Intravitreal NGF injection has been tested in the rat model of retinitis pigmentosa of the Royal College of Surgeons." (PMID 31823798, 2019). "The results of a recent pilot study indicated that topical administration of a total dose of 1 mg nerve growth factor (NGF) per patient with retinitis pigmentosa partly improved the visual function in some of the patients." (PMID 28573143, 2017). "Preclinical trials have shown beneficial effects of nerve growth factor (NGF) administration on visual function in animal models of retinitis pigmentosa (RP)." (PMID 26748988, 2016). "This study was partially supported by the project “NGF on Retinitis Pigmentosa” (RF-2010-2318561) to LA and MLR." (PMID 25897972, 2015). "Recently, we have reported that that eye NGF administration can protect also photoreceptor degeneration in a mice and rat with inherited retinitis pigmentosa." (PMID 25897972, 2015). "NGF injection rescues photoreceptor degeneration in the RCS rat model of retinitis pigmentosa, involving secondary effects by other neurotrophins such as FGF2 and VEGF." (PMID 19806208, 2009).